U2 (U2 spliceosomal RNA )
Gene: Small nuclear RNA gene on chromosome 9 (115,734,392 to 115,734,491, forward strand). Ensembl gene ENSG00000274755.
Gene Ontology:
Molecular function: pre-mRNA branch point binding
Biological process: mRNA branch site recognition
Cellular component: U2 snRNP
Homologues: Orthologues: macaque U2 (95% identical), rat LOC120103300 (59% identical), rabbit U2 (55% identical), mouse Gm22958 (54% identical). Paralogues in human: RNU2-28P (69% identical), RNU2-58P (65% identical), RNU2-24P (63% identical), RNU2-35P (63% identical), RNU2-41P (63% identical), U2 (63% identical), RNU2-72P (59% identical), RNU2-22P (58% identical), RNU2-53P (58% identical), RNU2-60P (57% identical), RNU2-10P (56% identical), RNU2-34P (56% identical), and 65 more.